KIF1A (kinesin family member 1A)
Diseases named in the same sentence as KIF1A in open-access papers (continued):
Sharing a sentence is not in itself a finding about the gene and the disease.
cancer (8 papers, 2009 to 2024). A tumor composed of atypical neoplastic, often pleomorphic cells that invade other tissues. "Here, we integrated a selected panel of datasets and performed a comprehensive pan-cancer analysis to identify potential important genes of NE differentiation, and identified Kinesin-like protein (KIF1A) as a potential regulator to promote NE differentiation." (PMID 39505875, 2024). "We performed a pan-cancer differential mRNA abundance analysis and identified that Kinesin-like protein (KIF1A) was highly expressed in NEPC." (PMID 39505875, 2024). "In summary, these results revealed that KIF1A acts as a promoter of aggressive cancer progression in NE transdifferentiated PCa cells." (PMID 39505875, 2024). "Multivariate analysis showed that KIF1A promoter methylation was inversely associated with DRC after adjusting for age, BMI, family history of cancer, menopausal status, alcohol use, smoking, multivitamin use and BC (p=0.012)." (PMID 24927296, 2014). "KIF1A (p=0.012) and OGDHL (p=0.048) were significantly associated with BC, after adjusting for age, family history of cancer and DRC." (PMID 24927296, 2014). "KIF1A may play a crucial role in biological processes, including positive regulation of T cell proliferation, primary immunodeficiency, pathways in cancer, the Wnt signaling pathway, and immune infiltrating cells." (PMID 37719786, 2023). "However, the function of KIF1A related to cancer is unknown." (PMID 20059769, 2010). "The data presented here suggest that KIF5B is implicated in several pathwaysinvolving lysosomes and that its highly expressed in all cancer cell lines tested,as compared to other N-Kinesins including KIF5A/KIF5C (Kinesin 1 family), KIF3A(Kinesin 2 family) and KIF1A (Kinesin 3 family)." (PMID 19242560, 2009).
infection (5 papers, 2013 to 2022). The state of being infected such as from the introduction of a foreign agent such as serum, vaccine, antigenic substance or organism. "In uninfected neurons, Kif1-A facilitates the anterograde transport of pre-synaptic and dense-core vesicles and is likely repurposed by Us9 during infection to modulate the axonal sorting and transport of virions." (PMID 23527020, 2013). "SARS-CoV-2 might also be using axonal transport proteins for its spread and infection in the neuron, as demonstrated by the mimicry of tubulin, KIF1A, KIF21A, and dynein." (PMID 33833673, 2021). "gE/gI is required for efficient anterograde transport of viral particles in axons by mediating the interaction between US9 and KIF1A early in infection, and when the interaction between US9 and KIF1A is weakened, the capsid stalls in in the axon." (PMID 35992696, 2022). "Since egress from cell bodies (not axons) occurs efficiently in the absence of Us9, and only a minority of egress vesicles sort into the axon late in infection, the kinetics of Kif1a-recruitment are not yet clear." (PMID 31995633, 2020).
neurodevelopmental disorder (4 papers, 2021 to 2024). A behavioral and cognitive disorder with onset during the developmental period that involves impaired or aberrant development of intellectual, motor, or social functions. "Here, we report a patient presenting a severe neurodevelopmental disorder carrying a novel de novo missense variant p.Arg169Thr (R169T) in the KIF1A motor domain." (PMID 34121983, 2021).
adenocarcinoma (1 paper, 2024). A common cancer characterized by the presence of malignant glandular cells. "Immunohistochemistry showed that KIF1A expression was elevated in post-treatment NEPC tissue compared to pre-treatment adenocarcinoma tissue." (PMID 39505875, 2024). "Particularly, KIF1A was up-regulated during the construction of LTL331R PDX model which mimicked the progression of PCa from adenocarcinoma to NEPC through castration." (PMID 39505875, 2024). "Importantly, we analyzed KIF1A expression by immunohistochemistry in two PCa cases, where the pre-endocrine treatment tissue was adenocarcinoma, while the post-treatment tissue displayed NEPC." (PMID 39505875, 2024).
autosomal dominant disease (1 paper, 2023). Autosomal dominant form of disease. "At present, we have classified the KIF1A:c.3826C>T variant as the cause of autosomal dominant disease." (PMID 37405542, 2023).
psychiatric disorder (1 paper, 2025). A disorder characterized by behavioral and/or psychological abnormalities, often accompanied by physical symptoms. "As a candidate for a crucial Kifs gene that is likely related to microglia polarization, we selected psychiatric disorder-related KIFs (KIF3A, KIF17, KIF1A, KIF1B, and KIF13A)." (PMID 39885501, 2025).
KIF1A also shares sentences with these, for which no sentence is quoted: peripheral neuropathy (4 papers); and motor neuron diseases (2); behavioral disorders (2); cerebellar ataxia (2); cortical visual impairment (2); Encephalopathy (2); epileptic seizure (2); frontotemporal dementia (2); glioma (2); Hypsarrhythmia (2); Parkinsonism (2); Progressive encephalopathy (2); Spasticity (2); Argininemia (1); Atrophy (1); autosomal dominant lower extremity-predominant spinal muscular atrophy-2A (1); autosomal dominant mental retardation (1); Autosomal recessive spastic ataxia of Charlevoix-Saguenay (1); autosomal recessive spastic paraplegia (1); Autosomal recessive spastic paraplegia type 30 (1); bipolar disorder (1); Borderline intellectual disability (1); brachydactyly (1); brain disorder (1); brain injury (1); cardiovascular diseases (1); cervical spondylosis (1); Charcot-Marie-Tooth disease (1); Cluster headache (1); corneal ulcer (1).
A further 32 diseases each share a sentence with KIF1A in 1 paper.